LAG3 (lymphocyte activating 3)
Diseases named in the same sentence as LAG3 in open-access papers (continued):
Sharing a sentence is not in itself a finding about the gene and the disease.
glioma (continued). "The frequency at which of CD8+ T cells expressed several of these immune targets, such as PD-1, LAG-3, CTLA-4, and CD39, was higher in the glioma microenvironment than in the PBMCs from patients with GBM and healthy donors." (PMID 32721947, 2020). "This is even critical because the role of LAG3 in glioma and the potential benefit of its modulation is not well established yet 93,94." (PMID 40520013, 2025). "Based on this, we believe that ACTN1 could be used as a target for regulating immune checkpoints, such as PD-1, TIM3, and LAG-3, to treat grade II/III gliomas." (PMID 38307919, 2024). "Specifically, we found that, as IGFBP5 levels increased, the expression of the seven immune checkpoint genes (BTLA, CD274, CTLA4, HAVCR2, LAG3, PDCD1, and PDCD1LG2) were increased and a large positive correlation was observed between IGFBP5 and these immune checkpoints in glioma." (PMID 38164271, 2024). "In addition to CTLA4, PD-1, and LAG3, other immunosuppression-related genes, like IGFBP2 and LGALS1 are highly expressed in patients with glioma." (PMID 37399661, 2023). "Given that, we hypothesized that NK CD56bright, Tfh, and macrophage cell types might be closely related to immune regulation in TME of glioma, and B7H3, PDCD1, LAG3 and CXCL16, CXCR4, CCR5 might be key targets for glioma immunotherapy." (PMID 35896732, 2022). "The result displayed that majority of the negative immune regulatory genes glioma were upregulated in the high-risk group, and the expression of immune checkpoint CTLA4 and immune checkpoint receptor LAG3 was notably higher in the high-risk group." (PMID 39279987, 2022). "Except for PD-1, CTLA4, and LAG3, the expression of other immunosuppression-related genes, such as LGALS1 and IGFBP2, is higher in glioma patients, and blocking the expression of immunosuppression-related genes can reshape the immunosuppressive microenvironment." (PMID 35928818, 2022). "It was evident that SIGLEC15, LAG3, and PDCD1 were highly expressed in glioma." (PMID 35663965, 2022). "To further validate the pro-tumoral role of LIGHT in glioma, we performed the Pearson correlation test to examine the relationship between LIGHT and immune checkpoint members, including HVEM, CTLA-4, PD-L1, PD-1, TIM3, LAG3, B7-H3, and B3-H4." (PMID 34513918, 2021). "Gliomas with a high TME-score expressed more immune checkpoints, such as LAG3, CD40, and PDCD1LG2." (PMID 34489938, 2021). "Therefore, the aim of this study was to evaluate LAG-3 expression in the tumor microenvironment of adult glioblastoma and WHO grade II–III glioma cases." (PMID 33651248, 2021). "LAG-3+ TILs were observed in 10/68 (14.7%) of glioblastoma samples while no tissue specimen of WHO grade II-III gliomas showed LAG-3+ TIL infiltration (p = 0.03, Fisher’s exact test)." (PMID 33651248, 2021). "Studies have revealed that the upregulation of immune checkpoints such as PD-1, LAG-3, and B7-H3 in glioma aids tumor immune evasion, resulting in T cell dysfunction, which suggests that NR2F6 may promote glioma immune evasion through upregulation of immune checkpoint expression." (PMID 37575237, 2023). "Correlation analysis showed that ZBTB42 was positively related to PD1, PD-L1, PD-L2, CTLA4, TIM3, and LAG3 in LGG and positively related to PD-L1, PD-L2, SIRPA in GBM, suggesting that the high expression of ZBTB42 may promote glioma progression via immune suppression microenvironment." (PMID 36762114, 2023). "Our research found that the expression levels of six immune checkpoint inhibitors (B7-H3, CTLA4, LAG3, PD-1, PD-L1, and TIM3) were increased with the increase in MELK expression, and significant positive correlations have been found between MELK and these immune checkpoints in glioma." (PMID 36353126, 2022).
glioma (continued). "Although HGGs are generally “cold tumors” due to its relatively low T cell infiltration in comparison with other tumors, ICI development is still may be a valid approach in gliomas, as CTLA-4, PD-1, TIM3, LAG3 and their corresponding ligands are expressed in these tumors." (PMID 36186781, 2022). "Indeed, the combination of anti-PD-1 with anti-LAG-3 antibodies has not been not shown to be superior than either treatment alone in a syngeneic glioma mouse model." (PMID 33651248, 2021). "Notably, the expression of TIM-3 and LAG-3 immune checkpoints is relatively low in gliomas, and as such these therapeutic targets are unlikely to be beneficial for the treatment of patients with glioma for most patients and especially as a monotherapy." (PMID 34440802, 2021). "Further, Tim-3 and other exhausting immune molecules (LAG-3, PD-1, CTLA4, CD244, and PD-1) exhibited significantly different expression profiles between normal brain tissues and GBM tissues according to the TCGA database, indicating their potential correlation with glioma progression." (PMID 33041828, 2020). "Other immune checkpoint molecules, including lymphocyte activation gene-3 (LAG-3; also known as CD223), 2B4 (also known as CD244), B and T lymphocyte attenuator (BTLA; also known as CD272), have not been fully explored for their biological activities and functions in glioma." (PMID 27756892, 2017). "Similarly, all LAG-3+ samples were from IDH-wildtype tumors (10/70, 14.3%) while no LAG-3+ TILs could be found in IDH-mutant glioma (p = 0.057, Fisher’s exact test)." (PMID 33651248, 2021). "Further, LAG-3+ TILs were only observed in WHO grade IV glioblastoma, while none of the investigated WHO grade II–III glioma presented with LAG-3+ TILs (p = 0.03)." (PMID 33651248, 2021). "have shown that LAG-3+ TILs are rarely observed in IDH-wt and absent in IDH-mt glioma." (PMID 34305910, 2021). "LAG-3+ TILs could be observed in 10/97 (10.3%) IDH-wildtype samples and in none of the included IDH-mutant glioma samples (p = 0.057)." (PMID 33651248, 2021).
ovarian carcinoma (81 papers, 2015 to 2026). A malignant neoplasm originating from the surface ovarian epithelium. "Immune checkpoint molecules such as TIM-3 and LAG-3 are associated with poor prognosis in ovarian cancer." (PMID 40649775, 2025). "Siglec-7 was found to be significantly overexpressed on tumor-infiltrating CD8+ T cells within colon cancer tissues and ovarian cancer ascites, associated with the presence of exhaustion markers PD-1 and LAG-3." (PMID 40547037, 2025). "Consistently, most studies, including a meta-analysis on NSCLC, renal cell carcinoma, ovarian cancer, gastric cancer, and a few other cancers, showed that expression of LAG3 on TILs is associated with better survival." (PMID 36765348, 2023). "The analyses also showed an association between LAG-3 expression and favorable survival in ovarian cancer." (PMID 36359346, 2022). "High ICOS and LAG-3 levels were significantly associated with longer survival in the ovarian cancer TCGA cohort." (PMID 33747935, 2021). "Both ICOS and LAG-3 were found to be significantly associated with improved overall survival in The Cancer Genome Atlas (TCGA) ovarian cancer cohort." (PMID 33747935, 2021). "PD-1 and LAG-3 co-expression has been previously reported in chronically stimulated CD8+ T cells or implicated in ovarian cancers." (PMID 27835902, 2016). "Additionally, in patients with ovarian cancer, LAG-3 and PD-1 co-expression is associated with the dysfunction or depletion of CD8+ T cells." (PMID 38627681, 2024). "Tumor-associated lymphocytes (TALs) from ovarian cancer patients confirmed that both CD8+ and CD4+ T cells exhibited elevated levels of LAG-3 and PD-1." (PMID 40649775, 2025). "The expression of various immune components is frequently compared to LAG-3 expression in ovarian cancer." (PMID 40649775, 2025). "The purpose of this study was to evaluate LAG-3 and TIM-3 protein expression in ovarian cancer tissue and its association with clinical features." (PMID 40649775, 2025). "In this study, we reveal that the co-expression of LAG-3 (Lymphocyteactivation gene 3) and PD-1 in ovarian cancer patients represents a novel and promising biomarker for predicting patient prognosis." (PMID 40895577, 2025). "Our team conducted a literature review on the role of T-cell immunoglobulin and mucin domain-containing protein 3 (TIM-3) and Lymphocyte Activation Gene 3 (LAG-3) in the tumor microenvironment and immunotherapy of ovarian cancer." (PMID 40649775, 2025). "In contrast, in other cancer types, such as HCC and ovarian cancer, higher LAG-3 expression generally represents a worse prognosis." (PMID 39660130, 2024). "Collectively, these data indicate that in PB- and MA-derived macrophages from high-grade ovarian cancer patients the increased frequency of TIGIT, CD226, TIM-3, and LAG-3 positive cells is associated with an M2 phenotype." (PMID 37876933, 2023). "In mouse models of ovarian cancer, co-blocking LAG3 and PD-1 expressed on CD4 + and CD8 + TILs induces enhanced anti-tumor response." (PMID 38115039, 2023). "The co-expression of LAG-3 and PD-1 has been shown to signify exhausted effector T cells in ovarian cancer, and thus simultaneous blocking of LAG-3 and PD-1 improves CD8+ T cell cytotoxicity." (PMID 36971124, 2023). "Lymphocyte-activating gene 3 (LAG3) associates with SHP-1/2, and LAG3/PD-1 collaboration limits CD8+ T-cell signaling, which dampened antitumor immunity in a murine ovarian cancer model." (PMID 38203502, 2023). "Expression of PD-1, CTLA-4, TIM-3 and LAG-3 significantly correlated with infiltrating immune cells in ovarian cancer." (PMID 36359346, 2022). "TIM-3 and LAG-3 were chosen for review because their expression appears to be clinically relevant in ovarian cancer, as we show in this article." (PMID 36359346, 2022).
ovarian carcinoma (continued). "For example, Huang and colleagues demonstrated in an ovarian cancer mouse model that the inhibition of PD-1 by a monoclonal antibody led to the compensatory upregulation of other immune checkpoints, such as LAG-3 or CTLA-4." (PMID 36289918, 2022). "LAG-3 expression in ovarian cancer has often been studied with the expression of other immune molecules." (PMID 36359346, 2022). "Isolated CD8+ positive tissue infiltrating lymphocytes from patients with ovarian cancer demonstrated significant upregulation in LAG-3 and high levels of PD-1." (PMID 36077354, 2022). "Immunosuppressive factors such as T cell immunoglobulin and mucin-domain containing-3 (TIM-3) or lymphocyte-activation gene 3 (LAG-3) in the tumor microenvironment are promising targets for immunotherapy for the treatment of ovarian cancer." (PMID 36359346, 2022). "To date, there are only a few trials using anti-LAG-3 antibodies in the treatment of ovarian cancer." (PMID 36359346, 2022). "TALs from ovarian cancer patients confirmed the upregulation of LAG-3 and PD-1 on both CD8+ and CD4+ T cells." (PMID 36359346, 2022). "For example, the overexpression of LAG-3 was detected on CD8+ TILs in ovarian cancer tumour tissues, and cytokine secretion was strongly decreased." (PMID 35494015, 2022). "The blockade of PD-1/CTLA-4/LAG-3 can efficiently inhibit ovarian cancer metastasis, thus showing a favorable outcome in reducing the risk of tumor metastasis." (PMID 34367975, 2021). "Tumor-infiltrating, antigen-specific CD8 T cells have been reported to be negatively regulated by LAG-3 in human ovarian cancer, and PD-1/LAG-3 co-expression in peripheral blood T cells is a biomarker of strong T cell dysfunctionality in lung cancer." (PMID 34067904, 2021). "A similar observation has been reported in a model of ovarian cancer in which therapeutic co-blockade of PD-1/LAG-3/CTLA-4 in WT mice leads to two times fewer tumor free mice compared to anti-LAG-3/CTLA-4 treatment in PD-1-/- mice." (PMID 33519801, 2020). "An overexpression of LAG-3 on tumor-infiltrating CD8+ T cells in different tumor types has also been reported for ovarian cancer, hepatocellular carcinoma, gastric cancer, and follicular lymphoma." (PMID 33396515, 2020). "In another study, the blockade of PD-1 resulted in the up-regulation of LAG-3 on CD8+ T cells in mouse ovarian cancer model." (PMID 31614877, 2019). "Matsuzaki J, Gnjatic S, Mhawech-Fauceglia P. Tumor-infiltrating NY-ESO-1–specific CD8+ T cells are negatively regulated by LAG-3 and PD-1 in human ovarian cancer." (PMID 30400822, 2018). "For instance, in NY-ESO-1 ovarian cancer samples, LAG-3 and PD-1 collaborate to mark dysfunctional CD8+ T cells, both of which attenuate CD8+ T cells activation, inhibit cytokines secretion, and take part in immune escape of tumor cells." (PMID 30603054, 2018). "The synergistic suppression of CD8+ T cell activity by LAG3 and PD-1 was further evaluated in a mouse model of ovarian carcinoma and revealed that physical interactions between these molecules contribute to this cooperative effect." (PMID 28275576, 2017). "The obtained results indicate that the expression of LAG-3 and TIM-3 proteins may be associated with specific clinicopathological features of ovarian cancer, such as histological type, FIGO stage, menopausal status, BMI, and patient age." (PMID 40649775, 2025). "Interestingly, LAG-3 expression has also been correlated with improved survival in ovarian cancer patients." (PMID 40649775, 2025). "Moreover, there is a strong correlation between immune cell infiltration and the expression of PD-1, CTLA-4, TIM-3, and LAG-3 in the ovarian cancer microenvironment." (PMID 40649775, 2025). "In the ovarian cancer model, the results suggested that the inhibition of the PD-1 or LAG-3 pathways alone was insufficient to control ovarian cancer, whereas the combined blockade with anti-LAG-3 and anti-PD-1 antibodies significantly delayed the growth of IE9mp1 ovarian tumors (P ═ 0.01)." (PMID 38581716, 2024).
ovarian carcinoma (continued). "A phase I trial indicated that tebotelimab blocks both the PD-1 and LAG-3 signaling pathways, displaying preliminary anti-tumor activity, particularly in ovarian epithelial cancer (PR, 11.1%), triple-negative BC (PR, 6.5%), and ICI-naïve NSCLC (ORR, 14.2%; CR, 7.1%)." (PMID 38627681, 2024). "Moreover, in another study in a murine ovarian cancer model, dual antibody blockade or genetic knockout of LAG-3 and PD-1 resulted in enhanced CD8+ T-cell effector function and subsequent delayed tumor growth." (PMID 37509517, 2023). "The presence of LAG3 in TILs from ovarian cancer has been previously reported." (PMID 36900156, 2023). "(ii) In a mouse model of ovarian cancer, tumour-infiltrating T cells coexpressed LAG-3 and PD-1." (PMID 35494015, 2022). "It was also observed in the murine ovarian cancer model that LAG-3 may collaborate in recruiting SHP1 or SHP2 to the TCR complex, thereby, negatively co-regulating T-cell signaling and function." (PMID 36077354, 2022). "In addition, therapies using anti-TIM-3 and anti-LAG-3 in ovarian cancer seem promising, especially in combination with other drugs, as we show in this article." (PMID 36359346, 2022). "In ovarian cancer, immune checkpoint molecules, such as LAG-3 and TIM-3, predicted poor survival." (PMID 36359346, 2022). "A study investigating ovarian cancer found that LAG-3 and PD-1 can down-regulate TILs." (PMID 34454491, 2021). "Indeed, previous studies in ovarian cancer also suggested a correlation of LAG-3+ TIL density with PD-1+ TIL density and therefore a marker for increased cancer-immune system interaction." (PMID 33651248, 2021). "Moreover, simultaneously inhibiting LAG-3 and PD-1 signaling can strengthen the T lymphocyte response in ovarian carcinoma." (PMID 34454491, 2021). "Many recent studies show a specific correlation between LAG3 and PD-1 with T cell inhibition in various diseases such as in viral infection, chronic tuberculosis, plasmodial infections, chronic lymphocytic leukemia, and ovarian cancer." (PMID 34267742, 2021). "The dual blockade of PD-1 and CTLA-4, conducted to simultaneously inhibit CD276, can help in inhibiting the activation of T cells and cytokine secretion, thereby also downregulating LAG-3 expression and improving antitumor immunity to achieve inhibition of ovarian cancer metastasis." (PMID 34367975, 2021). "Similarly in ovarian cancer patients, co-expression of LAG-3 and PD-1 was found on antigen-specific CD8+ T cells, and co-blockade of both lead to improved proliferation and cytokine production." (PMID 29535740, 2018). "Likewise, in a murine ovarian cancer model, LAG-3 and PD-1 are synergized to dampen CD8+ T cell effector function." (PMID 30603054, 2018). "Similarly, in TILs from patients with ovarian cancer, simultaneous LAG-3 and PD-1 blockade restores responsiveness of NY-ESO-1-specific LAG3+/PD-1+ CD8+ T cells to a greater extent than blockade of each coinhibitory receptor alone." (PMID 28443090, 2017). "Besides CTLA4, PD-1- and LAG3-expressing CD8+ T cells specific for tumor-derived antigen NY-EASO-1 were also detectable within the ovarian carcinoma infiltrates." (PMID 28275576, 2017). "Evaluation of LAG-3 and TIM-3 protein expression in ovarian cancer tissue and its role in distinguishing the clinical signs stated were the objectives of this study." (PMID 40649775, 2025). "LAG-3 and TIM-3 protein expression in ovarian cancer tissue samples was evaluated by immunohistochemistry." (PMID 40649775, 2025). "For instance, dual blockade of TIGIT and LAG-3 in ovarian cancer models overcame compensatory checkpoint upregulation, while a tri-specific PD-L1/TIGIT/LAG-3 antibody outperformed benchmark therapies in T-cell expansion and tumor suppression." (PMID 40567374, 2025).